TARBP2 (TARBP2 subunit of RISC loading complex)
Description:
Required for formation of the RNA induced silencing complex (RISC). Component of the RISC loading complex (RLC), also known as the micro-RNA (miRNA) loading complex (miRLC), which is composed of DICER1, AGO2 and TARBP2. Within the RLC/miRLC, DICER1 and TARBP2 are required to process precursor miRNAs (pre-miRNAs) to mature miRNAs and then load them onto AGO2. AGO2 bound to the mature miRNA constitutes the minimal RISC and may subsequently dissociate from DICER1 and TARBP2. May also play a role in the production of short interfering RNAs (siRNAs) from double-stranded RNA (dsRNA) by DICER1 (By similarity). Binds in vitro to the PRM1 3'-UTR (By similarity). Seems to act as a repressor of translation (By similarity). For some pre-miRNA substrates, may also alter the choice of cleavage site by DICER1. Negatively regulates IRF7-mediated IFN-beta signaling triggered by viral infection by inhibiting the phosphorylation of IRF7 and promoting its 'Lys'-48-linked ubiquitination and degradation. (Microbial infection) Binds to the HIV-1 TAR RNA which is located in the long terminal repeat (LTR) of HIV-1, and stimulates translation of TAR-containing RNAs. This is achieved in part at least by binding to and inhibiting EIF2AK2/PKR, thereby reducing phosphorylation and inhibition of EIF2S1/eIF-2-alpha. May also promote translation of TAR-containing RNAs independently of EIF2AK2/PKR. Mediates recruitment of FTSJ3 methyltransferase to HIV-1 RNA, leading to 2'-O-methylation of the viral genome, allowing HIV-1 to escape the innate immune system.
Synonyms: TRBP; LOQS; TRBP1; TRBP2
Tractability: PROTAC: ubiquitination databases record sites on it; its protein half-life has been measured; a small molecule that binds it is known.
Target class: Other nuclear protein
Gene: Protein-coding gene on chromosome 12 (53,500,921 to 53,506,431, forward strand). Ensembl gene ENSG00000139546.
Subcellular location: Cytoplasm; Cytoplasm, perinuclear region; Nucleus
Subcellular location (Human Protein Atlas): Nucleoplasm; Nuclear bodies
Pathways (Reactome):
Gene expression (Transcription): MicroRNA (miRNA) biogenesis; Small interfering RNA (siRNA) biogenesis
Immune System: PKR-mediated signaling
Gene Ontology:
Molecular function: double-stranded RNA binding; enzyme binding; identical protein binding; pre-miRNA binding; protein binding; protein homodimerization activity; protein sequestering activity; siRNA binding; pre-mRNA binding; miRNA binding
Biological process: miRNA processing; negative regulation of cytoplasmic pattern recognition receptor signaling pathway; negative regulation of defense response to virus by host; positive regulation of viral genome replication; pre-miRNA processing; regulation of viral transcription; RISC complex assembly; siRNA processing; negative regulation of protein kinase activity; regulation of regulatory ncRNA processing; post-transcriptional regulation of gene expression; regulation of miRNA processing; regulation of protein metabolic process; regulation of siRNA processing
Cellular component: cytoplasm; nucleoplasm; RISC complex; RISC-loading complex; cytosol; nucleus; perinuclear region of cytoplasm
Genetic constraint (gnomAD): Loss-of-function variants: 23 observed, 35.86 expected, observed/expected ratio (o/e) 0.64, 90% interval 0.46 to 0.91. The upper end of that interval is the gene's LOEUF score, 0.91, which puts it in group 3 of 6, group 1 being the genes least tolerant of losing a copy. Missense variants: 358 observed, 466.5 expected, observed/expected ratio (o/e) 0.77, 90% interval 0.7 to 0.84. Synonymous variants: 183 observed, 191.59 expected, observed/expected ratio (o/e) 0.96, 90% interval 0.85 to 1.08.
Homologues: Orthologues: chimpanzee TARBP2 (100% identical), macaque TARBP2 (99% identical), dog TARBP2 (98% identical), pig TARBP2 (97% identical), mouse Tarbp2 (95% identical), guinea pig TARBP2 (93% identical), rabbit TARBP2 (93% identical), rat Tarbp2 (91% identical), tropical clawed frog tarbp2 (67% identical), zebrafish tarbp2 (65% identical), Drosophila melanogaster loqs (29% identical), Drosophila melanogaster Zn72D (10% identical), and 3 more. Paralogues in human: PRKRA (39% identical), ADARB1 (22% identical), ADARB2 (22% identical), ADAR (22% identical), STAU2 (18% identical), ADAD1 (15% identical), ADAD2 (14% identical), STAU1 (11% identical), ZFR (11% identical), ZFR2 (11% identical), ILF2 (10% identical), ADAT1 (10% identical), and 2 more.
Diseases named in the same sentence as TARBP2 in open-access papers:
TARBP2 is named in the same sentence as 54 diseases in open-access papers, as found by Europe PMC text mining. Sharing a sentence is not in itself a finding about the gene and the disease. The quoted sentences say what the papers report.
breast carcinoma (9 papers, 2013 to 2023). "To investigate the association between TARBP2 and hypoxia, we utilized the cohort of breast cancer patients from the Cancer Genome Atlas (TCGA) and analyzed hypoxia scores, which were calculated using the mRNA-based signatures developed by Buffa and Winter." (PMID 35008634, 2021). "However, TARBP2 functions as an oncogene to contribute to malignant transformation and proliferation in cutaneous malignant melanoma and adrenocortical carcinoma, and its expression is associated with an unfavorable prognosis in patients with breast cancer." (PMID 30657254, 2019). "Taken together, this study indicates the regulatory role of TARBP2 in the ubiquitination–proteasomal degradation of HIF-1α protein in breast cancer." (PMID 35008634, 2021). "In this study, we found that TARBP2 expression is significantly correlated with induced hypoxia signatures in human breast cancer tissues." (PMID 35008634, 2021). "TARBP2 has been shown to enhance a transformed phenotype and tumorigenesis in vivo and is considered an unfavorable prognostic marker for breast cancer." (PMID 35008634, 2021). "Emerging evidence has shown the oncogenic role of TARBP2 in promoting cancer progression, making it an unfavorable prognosis marker for breast cancer." (PMID 35008634, 2021). "In support of our clinical findings that TARBP2 is correlated with tumor hypoxia, our IHC staining showed the positive correlation between HIF-1α and TARBP2 in human breast cancer tissues." (PMID 35008634, 2021). "Accumulating evidence has shown that the expression levels of TARBP2 are frequently deregulated in various human tumors, such as breast cancer, lung cancer, melanoma, and ewing sarcoma." (PMID 32305960, 2020). "In seven paired tissues, a higher level of TARBP2 protein was observed in five metastatic sites from breast cancer patients." (PMID 30759864, 2019). "In this study, we identified a novel mechanism of tamoxifen resistance in ER+ breast cancer cells through stabilization of TARBP2 protein and upregulation of SOX2." (PMID 30759864, 2019). "Tamoxifen-induced TARBP2 further stabilizes SOX2 protein to enhance desensitization of breast cancer cells to tamoxifen, while similar to TARBP2, its induction in cancer cells was also observed in metastatic tumor cells." (PMID 30759864, 2019). "In this study, we showed that TARBP2 is overexpressed in hormone therapy-resistant cells and breast cancer tissues, where it enhances tamoxifen resistance." (PMID 30759864, 2019). "Our previous results showed that TARBP2 is upregulated in tamoxifen-resistant breast cancer cells and tumors and that TARBP2 contributes to acquired resistance." (PMID 30759864, 2019). "Together, these results indicate that the upregulation of TARBP2 confers acquired resistance to tamoxifen in breast cancer cells." (PMID 30759864, 2019). "A recent study identified TAR (HIV-1) RNA binding protein 2 (TARBP2) as an oncogene that promotes breast cancer metastasis." (PMID 30759864, 2019). "TARBP2 might act as a tumor promoter in lung cancer, breast cancer, melanoma, hepatocellular carcinoma, adrenocortical carcinoma, and diffuse large B-cell lymphoma, but as a tumor suppressor in osteosarcoma and Ewing sarcoma." (PMID 36230863, 2022). "Moreover, the correlation between TARBP2 and the significantly downregulated E3 ligases were analyzed using the TCGA breast cancer patient database." (PMID 35008634, 2021). "Tamoxifen-induced TARBP2 expression results in the desensitization of ER+ breast cancer cells." (PMID 30759864, 2019). "Interestingly, we also found that TARBP2 expression was significantly upregulated in breast cancer compared with normal tissues in all datasets (18/18; 100%) in the Oncomine database." (PMID 30759864, 2019). "Upregulation of TARBP2 (12q12-q13), a cytoplasmic endonuclease which cleaves pre-miRs into 21 to 22 nucleotide mature miRs in conjunction with Dicer (DICER1), has been associated with metastasis in breast cancer." (PMID 27453764, 2016).
breast carcinoma (continued). "However, the Kaplan–Meier (KM) plot analysis revealed that ZC3H12A is a favorable marker for the prognosis of patients with breast cancer, which may counteract the mechanism of TARBP2-mediated deubiquitination of HIF-1α." (PMID 35008634, 2021). "Also, elevated TARBP2 level was observed in different subtypes of breast cancer." (PMID 30759864, 2019). "The protein expression of TARBP2 and HIF-1α was determined by IHC staining using a tissue microarray of human breast cancer." (PMID 35008634, 2021). "Having discovered that TARBP2 upregulates HIF-1α through inhibiting its proteasomal degradation, we investigated the correlation between TARBP2 and HIF-1α in patients with breast cancer." (PMID 35008634, 2021). "A positive correlation between TARBP2 and ZC3H12A (r = −0.19, p < 0.0001) was also observed in human breast cancer tissues." (PMID 35008634, 2021). "In agreement with our findings that SOX2 is a downstream of TARBP2 that modulates tamoxifen resistance, we also observed that SOX2 expression is correlated with poor prognosis of ER+ breast cancer patients." (PMID 30759864, 2019). "In contrast, no significant induction of TARBP2 was found in the ER- breast cancer cell lines SKBR3, Hs578T, and MDA-MB-231." (PMID 30759864, 2019). "As an RNA‐binding protein, TARBP2 enhances invasion and metastatic colonization by directly binding APP and ZNF395 transcripts, thereby post‐transcriptionally enhancing their decay rate in breast cancer." (PMID 30657254, 2019). "To confirm these effects in different ER+ breast cancer cells, we used ZR-75-1 cells for treatment with tamoxifen or 4-OHT and observed similar dose-dependent effects of both drugs on the induction of TARBP2 expression under short-term and noncytotoxic treatments." (PMID 30759864, 2019).
Ewing sarcoma (7 papers, 2014 to 2022). A small round cell tumor that lacks morphologic, immunohistochemical, and electron microscopic evidence of neuroectodermal differentiation. "Importantly, miR-145 has shown a negative regulation of SERPINE1 in human endometriotic cell line, and the expression of mature miR-145 was decreased in TARBP2-depleted Ewing sarcoma family tumor cell lines." (PMID 34249676, 2021). "Additionally, TARBP2 expression is reduced in several cancers, including colorectal cancer, gastric cancer, and Ewing sarcoma." (PMID 30657254, 2019). "Similarly, the systemic injection of 30 μg of synthetic TARBP2-dependent miR-143 or miR-145 showed a significant reduction of tumor volume, suggesting that CSC phenotypes of Ewing sarcoma correlate with the deregulation of TARBP2-dependent miRNA expression." (PMID 28115942, 2016). "Moreover, mir145 and SOX2 are regulated by EWS-FLI1, and TARBP2 dependent miRNA maturation appears to be a major regulatory determinant of the cancer stem cells in Ewing sarcoma." (PMID 25243408, 2014). "They found that TARBP2 (TAR RNA-binding protein 2), which forms part of the Dicer-1 complex, was suppressed in CD133+ Ewing sarcoma cells as well as hpMSCEWS-FLI-1, and enoxacin, which augments TARBP2 function, inhibited tumor growth through the restoration of miRNA maturation." (PMID 28115942, 2016).
hepatocellular carcinoma (7 papers, 2019 to 2024). A malignant tumor that arises from hepatocytes. "AcRoots also suppressed DLX2/TARBP2/JNK/AKT pathway to inhibit hepatocellular carcinoma cell proliferation and metastasis." (PMID 35152841, 2022).
gastric cancer (6 papers, 2013 to 2024). A primary or metastatic malignant neoplasm involving the stomach. "In summary, LINC01526 promoted gastric cancer progression by interacting with TARBP2, which subsequently degraded GNG7 mRNA." (PMID 36230863, 2022). "Decreased expression of TARBP2 was reported in colorectal and gastric cancers presenting microsatellite instability." (PMID 23671264, 2013). "TARBP2 gene mutations causing a loss of TARBP protein expression have been previously shown in colorectal and gastric cancers." (PMID 23671264, 2013). "Finally, the rescue assay disclosed that LINC01526 promoted gastric cancer progression by interacting with TARBP2, leading to the degradation of GNG7 mRNA." (PMID 36230863, 2022). "SMAD3, phosphorylated by TGF-β, translocates to the nucleus, binding to the TGILR promoter and promoting its transcription; TGILR sustains TARBP2 protein stability, hastening TARBP2-mediated degradation of miR-1306 and miR-33a, and upregulating TCF4, thereby advancing gastric cancer progression." (PMID 39717771, 2024). "A Korean study of 2010 evaluated AGO1, AGO2, TNRC6A, TNRC6C, TARBP2 and XPO5 mutations in colorectal (CRC) and gastric cancers (GC), with or without microsatellite instability." (PMID 23586049, 2013).
adrenocortical carcinoma (5 papers, 2013 to 2022). "In adrenocortical cancer, two studies analyzed Tarbp2, Dicer1, and Drosha expression in ACA and ACC." (PMID 26834703, 2015).
lung carcinoma (5 papers, 2020 to 2024). "In lung cancer, RNA binding protein TARBP2-mediated deposition of m6A in target transcripts inhibits efficient splicing to increase the rate of intron retention." (PMID 35093087, 2022). "As a promoter of lung cancer growth, TARBP2 recruits the methyltransferase complex to deposit m6A marks on transcripts, thereby resulting in intron retention with the help of the splicing factor SRSF1." (PMID 35093087, 2022). "Indeed, RT–PCR results indicated that the deletion of MEN1 in lung cancer cells increased the instances of short splicing isoforms in the FAM189B, NUBP2, ENDOV and TARBP2 genes, but inhibited generation of the CPSF7, MRRF and LETMD1 splicing isoforms." (PMID 37395406, 2023).
melanoma (4 papers, 2020 to 2024). A malignant, usually aggressive tumor composed of atypical, neoplastic melanocytes. "In addition, TARBP2 expression levels were significantly higher in metastases type of melanoma (CMMM) compared to primary melanoma (PCMM), and SND1 expression levels were significantly higher in CMMM compared to PCMM and BMN." (PMID 36982460, 2023).
adenoma (3 papers, 2013 to 2021). A neoplasm arising from the epithelium. "On the other hand, transactivation region (human immunodeficiency) ribonucleic acid (TAR (HIV) RNA) binding protein 2 (TARBP2) gene overexpression seems to be a discriminating factor between ACCs and adenomas." (PMID 32635927, 2020). "Twenty-seven patients with ACCs were correctly predicted based on the expression of TARBP2 mRNA (27/29 patients, 93% sensitivity); however, 10/43 adenoma cases were misclassified, leading to a specificity of 76%." (PMID 23671264, 2013). "In the adenomas, TARBP2 staining was mainly confined to oxyphilic cells while the preponderance of lipid-rich cells was negative for TARBP2 immunoreactivity." (PMID 23671264, 2013). "Among the adenomas, most of the cases (12/17) presented mixed or positive nuclear TARBP2 expression in oxyphilic cells while the remaining five cases showed negative staining in the nuclei of the same cell type." (PMID 23671264, 2013). "To further confirm this over-expression, we evaluated the protein level of TARBP2 in a subset of adrenocortical tumors (17 adenomas and 17 carcinomas) and five normal adrenal glands using immunohistochemistry." (PMID 23671264, 2013). "Particularly, TARBP2, DICER and DROSHA miRNA-target genes are significantly overexpressed in ACCs when compared with adenomas and normal adrenal tissue samples." (PMID 34829730, 2021). "Our results show a significant over-expression of TARBP2, DICER, and DROSHA in the carcinomas compared with adenomas or adrenal cortices (P<0.001 for all comparisons)." (PMID 23671264, 2013). "By contrast, abnormal mRNA expression of TARBP2, DICER, and DROSHA was less frequent in adenomas (TARBP2, 32% (14/43); DICER, 37% (16/43); and DROSHA, 40% (17/43))." (PMID 23671264, 2013). "In summary, we report frequent over-expression of TARBP2 in ACC and we found that TARBP2 mRNA expression level is a useful predictor of ACC and able to discriminate adenomas from carcinomas." (PMID 23671264, 2013). "We show that TARBP2, DICER, and DROSHA are significantly over-expressed in ACC when compared with adenomas and adrenal cortices." (PMID 23671264, 2013). "Here, we evaluated the mRNA expression of DROSHA, DGCR8, DICER (DICER1), TARBP2, and PRKRA, the core components in the miRNA biogenesis pathway, in a cohort of 73 adrenocortical tumors (including 43 adenomas and 30 carcinomas) and nine normal adrenal cortices using a RT-qPCR approach." (PMID 23671264, 2013). "Twelve of the 17 adenomas (70%) showed a moderate cytoplasmic staining, four cases (24%) demonstrated weak or negative TARBP2 expression while only one case presented strong TARBP2 immunoreactivity." (PMID 23671264, 2013). "Significant over-expression of TARBP2 (1.3- to 4-fold, P<0.0001), DICER (0.4- to 5-fold, P<0.0001), and DROSHA (0.2- to 4.5-fold, P<0.0001) was also observed in carcinomas when compared with adenomas." (PMID 23671264, 2013). "As the TARBP2 gene is located in the chromosomal region 12q13.13 that is frequently gained/amplified in ACC, we investigated TARBP2 gene copy number alterations in a subset of 28 carcinomas, 18 adenomas, and 3 normal adrenal cortices using TaqMan copy number assay." (PMID 23671264, 2013). "Furthermore, we demonstrate that mRNA expression of TARBP2, but not DICER or DROSHA, is a strong molecular predictor to discriminate between adenomas and carcinomas." (PMID 23671264, 2013).
prostate carcinoma (3 papers, 2013 to 2025). A carcinoma that arises from epithelial cells of the prostate gland. "Research has shown that TARBP2 is often dysregulated in various cancers, including prostate cancer and colorectal cancer." (PMID 39819815, 2025). "In line with our findings, over-expression of TARBP2 and DICER was observed in prostate cancer." (PMID 23671264, 2013).
viral infections (3 papers, 2022 to 2025). "Previous studies have proved that TARBP2 participates in viral infections, micro RNA biogenesis, and tumorigenesis." (PMID 36230863, 2022). "Additionally, TARBP2 has multiple functions in modulating virus infections and the host immune response." (PMID 39819815, 2025).
adrenocortical adenoma (2 papers, 2015 to 2020). "Recently, TRBP overexpression was demonstrated in ACCs and TARBP2 gene expression was useful to discriminate between adrenocortical adenomas and carcinomas." (PMID 26087193, 2015). "Regarding TARBP2 gene expression, TARBP2 mRNA levels were similar between adrenocortical adenomas (median 0.54; range, 0.1 to 9.7) and ACCs (0.52; 0.1 to 2.7, p = 0.71)." (PMID 26087193, 2015). "In contrast to this previous data, TARBP2 gene and protein (TRBP) expression was not different between adrenocortical adenomas and ACCs in our cohort of ACTs." (PMID 26087193, 2015).
liver cancer (2 papers, 2019 to 2021). An epithelial or non-epithelial malignant neoplasm that arises from the liver. "In particular, TARBP2 expression was relatively decreased in liver cancer and pancreatic cancer, suggesting that TARBP2 levels were suppressed in liver and pancreatic tumors." (PMID 30657254, 2019). "In the current report, we aimed to examine TARBP2 for its role in HCC progression and to explore related regulatory pathways, taking advantage of clinical specimens and well-characterized liver cancer/normal liver cell lines." (PMID 34249676, 2021).